CCND1 (cyclin D1)
Diseases named in the same sentence as CCND1 in open-access papers (continued):
Sharing a sentence is not in itself a finding about the gene and the disease.
cancer (continued). "Moreover, CuONPs inhibited cell growth and induced apoptosis in various cancer cells by regulating the expression of BCL-2, BAX, and CCND1." (PMID 38813193, 2024). "Gene expression analysis suggests that its mechanism of action may involve downregulation of cancer-related genes such as AKT1, BCL2L1, CCND1, CDK4, PLK1, and RHOA." (PMID 38751791, 2024). "Amplifications of CCND1, CCND2, and CCND3 are frequently observed across multiple cancer types." (PMID 38612902, 2024). "Our result revealed that there was a negative correlation between the CCND1 gene's methylation levels and its expression in multiple types of cancer, particularly in ESCA, HNSC, and STAD." (PMID 39188436, 2024). "Across various types of cancer (BLCA, CHOL, COAD, ESCA, READ, and UCEC), the CCND1 gene expression was statistically significant when comparing normal tissue samples with normal weight, extreme weight, obese, and extremely obese patients' samples with varying degrees of significance." (PMID 39188436, 2024). "Bcl-2, Survivin, IAP-1, Cyclin D1, and COX-2 are some of the key proteins involved in opposing apoptosis, relaying survival signals, driving the cell cycle, and promoting inflammation in cancer cells." (PMID 37835375, 2023). "In various cancer cell lines, CARTPT acts an oncogene, enhancing cellular survival by the activation of the ERK pathway, the stimulation of other pro-survival molecules, the inhibition of apoptosis or the increase in cyclin D1 levels." (PMID 37373130, 2023). "Beyond their role in immunity, all of these factors contribute to keeping the level of NF-kB activation high, and persistent inducing and amplifying side effects of NF-kB such as cyclin D1 and c-MYC transcription, which in turn, play important roles in cancer progression." (PMID 37108333, 2023). "Cyclin D1 (CCND1), a crucial mediator of cell cycle progression, is the major cyclin involved in transition of cells from the G1 to S phase and plays a vital role in the pathogenesis of cancer." (PMID 37024471, 2023). "However, we found that c-MYC S405A cancer cells had lower c-MYC, cyclin D1, and CDK4 expression than c-MYC WT cancer cells, while c-MYC S405E cancer cells had higher c-MYC, cyclin D1, and CDK4 expression than c-MYC WT cancer cells." (PMID 37596667, 2023). "Although cyclin D1 has been regarded as an oncogenic driver in cancers, the prognostic effects of cyclin D1 have been inconclusive thus far, as no consensus has been reached." (PMID 36675501, 2023). "Cyclin D1 is mainly known as an oncogenic driver in cancers, and the dysregulated cyclin D1/cyclin-dependent kinase (CDK) 4/6 axis is considered an attractive target for cancer therapy." (PMID 36675501, 2023). "To study the mechanisms underlying cell proliferation, we analyzed the effects of the compounds, both individually and in combination, on the gene expression of two cancer-related genes: the oncogenic voltage-gated potassium channel subfamily H member 1 (KCNH1) gene and the cyclin D1 gene (CCND1)." (PMID 38004441, 2023). "Cyclin D1, epidermal growth factor (EGFR) and vascular endothelial growth factor (VEGR) are common carcinogenic proteins that have potential therapeutic targets in various cancers." (PMID 38414954, 2023). "The dysregulation of cyclin D1 transcription as well as assembly and hyperactivation of its cognate CDK result in uncontrolled cell growth, so cyclin D1 has been regarded as an oncogenic driver in cancers." (PMID 36675501, 2023). "In addition, we identified recurrent CNVs in regions of well-recognized cancer-driving genes (EGFR, MTOR, CCND1, and MYC) or tumor suppressor gene (RB1), with a relatively higher variation in the DN and T stages." (PMID 36914617, 2023).
cancer (continued). "In BET bromodomain inhibitor JQ1‐resistance HCT116 cells, which showed high resistance to various anti‐cancer drugs, including cisplatin, TNIK (TRAF2 and NCK‐interacting protein kinase) was a regulator of Wnt/β‐catenin signaling and transactivate cyclin D1 (CCND1) and cyclin E1 (CCNE1)." (PMID 36408691, 2023). "They did not observe any synergistic effect of cortactin on cyclin-D1-induced mammary hyperplasia or carcinoma nor the development of distant metastasis." (PMID 37761244, 2023). "Cyclin D1 regulates the transition of cells from the G1 into S phase, and high level of cyclin D1 is correlated with poor prognosis and negative cancer outcomes." (PMID 35992826, 2022). "Further, we found cyclin D1 downregulation could be an important mechanism for CZE and CIN to arrest the cell cycle in the cancer cells." (PMID 35774603, 2022). "In addition, NF-κB downstream effectors, such as CCND1, CCNE2, MET, VEGFA, CD44 and CD133, contribute to cancer proliferation, metastasis and stemness, and their expression is regulated by PCDH1." (PMID 35864095, 2022). "Piperlongumine inhibits cancer growth by inducing the accumulation of intracellular ROS, decreasing glutathione, damaging chromosomal DNA, and modulating key regulatory proteins, including PI3K, AKT, mTOR, NF-κB, STATs, and cyclin D1." (PMID 35954218, 2022). "In FGFR-aberrant cancers, MYC or CCND1 amplifications can indeed confer resistance to FGFRi48–50." (PMID 35948633, 2022). "Both CCND1 and CCND2 have been previously reported as deregulated in many cancers." (PMID 35879975, 2022). "Cyclin D1 interacts with class I/II HDACs to regulate c-Myc expression, thus making the combinations of RTK targeted therapies and HDACi important strategies for cancer therapy." (PMID 35057104, 2022). "CCND1, CCND3, and CCND2 have different roles in cancer depending on cell and tissue types." (PMID 36313570, 2022). "The administration of DRB revealed a negative effect on cancer cell proliferation by repressing the expression of nuclear β-catenin, cyclin D1, and c-Myc." (PMID 36360101, 2022). "The overexpression of CCND1 is a common event in cancer but does not occur solely as a consequence of gene amplification." (PMID 34901460, 2022). "In our mouse model of PDAC lacking Polθ, we demonstrate that cyclin D1 expression increases with cancer progression, characterized by an increased presence of high-grade PanINs in older animals." (PMID 36077614, 2022). "In total, FISH results on both 6q15 deletions and alterations of HER2, CCND1, MYC, MDM2, PTEN, 8p21, and 9p21 were available in subsets of 921 (HER2), 1007 (CCND1), 699 (MYC), 1022 (MDM2), 980 (PTEN), 986 (8p21), and 902 (9p21) cancers." (PMID 34625909, 2022). "In addition, SOX2 regulates cyclin D1 and CD133 in cancer cells, affecting cancer cell proliferation and generation." (PMID 35562862, 2022). "Moreover, the levels of HIF-1α, Cyclin D1, c-Myc, and OCT4 were elevated in TRIB2-overexpressed cancer cells, which further promote cancer cell proliferation." (PMID 35790734, 2022). "Using qPCR assay for known genes modulated NT157 in other cancer models, we identified that NT157 decreased expression of oncogenes BCL2, CCND1, MYB, and MYC and increased genes related to cellular stress and apoptosis, JUN, BBC3, CDKN1A, CDKN1B, FOS, and EGR1 (all p < 0.05)." (PMID 36224313, 2022).
cancer (continued). "Cyclin D1 (CCND1) is an important regulator of G1 to S phase progression in many different cell types, which is important for the development and progression of several cancers, including those of the breast, esophagus, bladder, lung, and eye." (PMID 34901460, 2022). "Cyclin D1 overexpression leads to elevated cancer growth and negatively affects functions of proteins involved in DNA repair including BRCA1/2." (PMID 34677582, 2021). "Although Cyclin D1 is not essential for entry into cell cycle progression, its amplification/overexpression in human tumors is oncogenic as it allows cancer cells to proliferate independent of extracellular growth signaling cues." (PMID 34888236, 2021). "The proliferation and invasion of several cancers could be explained by STAT3 activation and cyclin D1 overexpression." (PMID 35003089, 2021). "But we have not found the researches concerning the new function of cyclin D1 on human cancer cells." (PMID 34335935, 2021). "Cyclin D1 is frequently overexpressed in human cancers and has been reported to be a carcinogenic driver in most of these cancers, and CDK inhibitors targeting cyclin D1 are considered a feasible method for cancer treatment." (PMID 34766149, 2021). "Overexpression USP22 is a marker of aggressive cancer phenotypes like metastasis, and therapy resistance studies have shown that catalyzing SAGA subunit USP22 to control CCND1 ubiquitination is important for the progression of cancer cells through the G1 cell cycle." (PMID 33498168, 2021). "Because CCND1 is a cell cycle regulatory protein that influences cell proliferation and has cancer-promoting properties in many tumors including GC, JARID1B may promote cell proliferation through CCND1." (PMID 34778074, 2021). "Of note, restraint of USP2 function induced growth suppression only in the cancer cells addicted to cyclin D1 expression, whereas there was no major effect on cell growth of normal human fibroblasts." (PMID 34072267, 2021). "SRY-box transcription factor 6 (SOX6) levels are inversely correlated with metastasis in cancer, and CDKN1A and CCND1 are upregulated and downregulated, respectively, by SOX6, suggesting that its tumor-suppressive function is associated with cell cycle regulation." (PMID 33435156, 2021). "In order to explore the molecular mechanism via which CDC37L1 inhibited GC cell proliferation and migration, we detected the expression of several cancer signaling pathway factors, such as CDK4, CDK6, Cyclin D1, FAK, PI3K-P110 and mTOR through western blot assays." (PMID 33976724, 2021). "Moreover, the authors found that hypermethylation of the CCND1 promotor is specific for GCTB and therefore cyclin D1 is a plausible cancer-driver gene." (PMID 34680268, 2021). "Furthermore, cyclin D1 is related to cell proliferation, migration, EMT and chemoresistance in several types of cancers." (PMID 34716310, 2021). "In cancer progression, VRK1 promotes the G1/S transition through phosphorylating the cAMP response element (CRE)-binding protein (CREB), thereby enhancing the binding affinity of CREB to the cyclin D1 (CCND1) promoter." (PMID 34071140, 2021). "CCND1 and CCND2 belong to the D‐type cyclins and are usually considered promoters of human cancer." (PMID 33473276, 2021). "MYC, CDK2, and cyclin D1 (highlighted by red circles) as part of the CCT2 interactome are shown, supporting that CCT2 could be a central point or node for regulation of cancer proliferation pathways mediated by these factors." (PMID 33996588, 2021).
cancer (continued). "Other cancer amplified genes that also significantly increase ARE reporter activity are MYC (a previously known gene to exert post-transcriptional effect), MYCN, CCND1, CCNE1, SKP2, and NOTCH2." (PMID 34535639, 2021). "The effects of HA on cancer cells may be mediated through its receptor CD44, which triggers a cascade of signal transduction increases, including increases in PI3K, Cyclin D1 and CDK4." (PMID 32517712, 2020). "We found that the protein levels of CDK4 as well as p-RB and Cyclin D1 were down-regulated by wogonin in RCC cells, suggesting that wogonin may exert anti-cancer efficacy by suppressing CDK4 and Cyclin D1 expression." (PMID 32792963, 2020). "Similarly, since we observed the decrease of mRNA export and of protein expression of c-MYC and cyclin D1 by disruption of the API5−FGF2 complex formation, the API5−FGF2 interaction can be an additional potential therapeutic target for cancers." (PMID 32383752, 2020). "A study has also shown that matrine derivatives, which are one of the main components of CKI, can be downregulated, CCND1, and attenuated the PI3K/Akt pathway to induce G1 cell cycle arrest and autophagy in cancer cells through immunofluorescence analysis, western blotting and murine models." (PMID 32728182, 2020). "The downregulation of CDK18 RNA in cancer blood (metastatic and non-metastatic grouped together) compared to normal was significant with p value = 0.001, whereas CCND1 was downregulated with p = 0.039." (PMID 32013938, 2020). "We found that AIM suppressed NF-κB activation induced by TNF-α in MCF-7 cells, and the upregulation of NF-κB-regulated genes (COX-2; MMP-2, MMP-9, and VEGF) involved in cancer cell proliferation (COX-2, C-myc, Cyclin-D1), and invasion, adhesion, and angiogenesis (MMP-2, MMP-9, ICAM-1, VEGF)." (PMID 32455624, 2020). "The CCND1 involved in cell cycle progression; TEAD4, a transcription factor in the Hippo signaling pathway; and EIF4EBP1, the translational regulator in PI3K/Akt/mTOR signaling, have been found to be significantly deregulated in several cancers." (PMID 32908901, 2020). "It is important to note that CCND1 and c-MYC are the classic proto-oncogenes involved in regulation of cell cycle and proliferation, thus playing a critical role in development of various types of malignant tumors." (PMID 33007980, 2020). "Taken together, miR-584 may have an unvalidated cancer-related targetome that includes PTEN, CCND1, PIK3CA and STAT1." (PMID 32615958, 2020). "The CDK4/6-RB axis is critical for cell cycle entry and not surprisingly most cancers subvert this axis to promote proliferation; for instance, 19% of BC show amplification of CDK4 and CCND1 amplification is associated with endocrine resistance." (PMID 32307447, 2020). "Analysis of expression profiles from the cohort of 94 HNSCC cases revealed that the mean expression of CCND1 does not differ between the normal mucosae and carcinomas." (PMID 32224897, 2020). "Consistently, there was a significant negative correlation between hepatic cyclin D1 gene expression and cell death and a significant positive correlation between cyclin D1 expression and cancer metastatic capability (as assessed by the MMP-2:TIMP-1 ratio)." (PMID 31836811, 2019).
cancer (continued). "Some of these targets are oncogenes, for example, CCND1 and KRAS, or tumour suppressors such as PTEN and HSP90AA1, and the deregulation of these genes may contribute to cancer pathogenesis." (PMID 30845775, 2019). "In this study, the expression of BRCA2 was up-regulated, while CCND1 protein was down-regulated, which indicated that the infection might inhibit the growth of BREAST cancer." (PMID 30792708, 2019). "In ER+ cancer cells, PIP5K1α acted on pSer-473 AKT, and was in complexes with VEGFR2, serving as co-factor of ER-alpha to regulate activities of target genes including cyclin D1 and CDK1." (PMID 30104711, 2019). "With regards to known cancer drivers, 24 showed alterations, including the oral cell lineage transcription factors TP63 (amplified, 21.94%) and SOX2 (amplified, 20.97%), CDKN2A, CCND1 (amplified, 24.27%), PIK3CA (amplified, 20.97%) and EGFR (amplified, 10.67%)." (PMID 31703248, 2019). "PTEN, BRCA1, and BRCA2 proteins play an important role in resisting the growth of BREAST cancer, while PI3K and CCND1 proteins could improve the growth of BREAST cancer." (PMID 30792708, 2019). "Gene expression analysis revealed that its mechanism of action might be attributed, in part, to downregulation of cancer-related genes, such as AKT1, BCL2L1, CCND1, CDK4, PLK1, and RHOA." (PMID 31527550, 2019). "In HCT-15 cells, reduced transcription of cell cycle mediating genes (CCND1, PCNA, CDK2, CDKN1B), and reduced transcription of anti-apoptotic genes (BMI1, BIRC5 and BCL2), support a cancer suppressive and favorable FOXO3/FOXM1 ratio upon combined TNKSi/MEKi treatment." (PMID 30717152, 2019). "Since CCND1 is one of the target genes of the WNT signaling pathway, and this signaling pathway has become a therapeutic target in various cancer types, we speculated that ivermectin treatment may have effects on WNT signaling." (PMID 31375107, 2019). "As FBXW8-meditated cyclin D1 and HPK1 degradation was necessary for cancer cell growth." (PMID 30341246, 2019). "Future studies should further explore the relationship between 4EBP1 and Cyclin D1 in cancer cells and non-transformed cells." (PMID 31122207, 2019). "In addition, levels of c-Myc, Cyclin D1, survivin and c-Jun proteins were increased with increases in RON/RONΔ160 and β-catenin expression in cancer tissues." (PMID 31085796, 2019). "Finally, biochemical and cell imaging experiments in human cancer cells reveal that the O-GlcNAc transferase (OGT) binds to and glycosylates cyclin D1." (PMID 30853938, 2019). "CASP8, CCND1, DAPK1 and PSA are involved in pathways in cancer." (PMID 30867653, 2019). "Since β-catenin regulates the expression of a considerable number of genes, such as CYCLIN D1 and cMYC, it is not surprising that this signaling interferes in numerous cancer-generating processes." (PMID 31803621, 2019). "Overexpression of CCND1 and MYC in cancer is investigated and confirmed." (PMID 34466490, 2019). "Besides, KHDRBS1 regulates the alternative splicing of several genes, most of them involved in human cancer, such as CD44, Bcl-xl, Sgce, SMN2, SF2/ASF, and Cyclin D1." (PMID 31440515, 2019). "Thus, many WNT/β-catenin target genes such as c-Myc, cyclin D1, and HIF-1α are involved in the development of cancers." (PMID 29706964, 2018). "The CCND1 gene is amplified in a variety of cancers, including approximately 20% of muscle-invasive and non-muscle-invasive bladder cancers, and its upregulation by mutant FGFR3 is therefore predicted to contribute to FGFR3-dependent oncogenesis." (PMID 29423038, 2018).